VEGFA (vascular endothelial growth factor A)
Diseases named in the same sentence as VEGFA in open-access papers (continued):
Sharing a sentence is not in itself a finding about the gene and the disease.
breast cancer (continued). "Determination of VEGFA mRNA levels in breast cancer tissue by Semi-quantitative reverse transcription PCR revealed that −634 CC genotype was significantly associated with highest VEGFA mRNA when compared to GG and GC genotype." (PMID 23203097, 2012). "This evidence supports the crucial role of VEGFA in the transition from benign to malignant breast disease and breast cancer aggressiveness." (PMID 23203097, 2012). "In advanced breast cancer patients receiving bevacizumab and vinorelbine who had lower baseline plasma VEGFA before treatment had longer time to progress (9.3 months vs. 3.7 months) than those with higher plasma VEGFA." (PMID 23203097, 2012). "Determination of VEGFA expression in breast cancer tissue by immunohistochemistry can distinguish the source of VEGFA, but revealed null results." (PMID 23203097, 2012). "Alteration of C to T at position 936 in 3′ UTR had protective effect against breast cancer and had a trend of correlation with lower plasma VEGFA levels." (PMID 23203097, 2012). "In addition, overexpression of vascular endothelial growth factor A (VEGFA) in breast cancer cells due to mechanical compression, was induced via DNA methyltransferase 3 alpha (DNMT3A)- dependent miR-9 reduction." (PMID 40171226, 2025). "Additionally, VEGF/VEGFR2 signaling has been shown to promote STAT3 activation leading to self-renewal of breast cancer cells in vitro and VEGFA induces LEC migration and tube formation via STAT3 signaling." (PMID 38218743, 2024). "In addition, in a murine model of breast cancer, macrophage-specific depletion of VEGFA reduced both vascular permeability and circulating tumor cells while restoring vascular junctions." (PMID 39761010, 2024). "Therefore, the understanding of the biological effect of the different VEGFA isoforms and their role in breast cancer angiogenesis would be critical to developing novel inhibitors of the VEGF/VEGFR pathway." (PMID 39302921, 2024). "This factor induces the upregulation of miR-222-3p that, in turn, inhibits SRSF2 expression at a post-transcriptional level by binding its 3′ UTR, finally resulting in the aberrant expression of Vascular Endothelial Growth Factor A (VEGFA) isoforms in breast cancer." (PMID 38893242, 2024). "Moreover, it was found experimentally that administering miR-205-5p and miR-141 in breast cancer tissues can reduce VEGFA metastasis and induce apoptosis." (PMID 39614097, 2024). "In addition, suppression of VEGFA enhances the invasion and migration while inhibiting the apoptosis of breast cancer cells." (PMID 38737443, 2024). "In breast cancer, the VEGFA expression is positivity significantly correlated with PD-L1, and VEGFA may be a predictor of immune characteristics and serves as a useful biomarker for immune targeted therapy." (PMID 38687357, 2024). "Moreover, VEGFA expression is critical for angiogenesis and vasculogenic mimicry formation in breast cancer." (PMID 38392969, 2024). "Moreover, we found that the PD-L1-deficient breast cancer cells (MDA-MB-231 and MDA-MB-436) exhibited decreased levels of EGR1 and VEGFA." (PMID 36977660, 2023). "Our findings suggest that KLF2 may inhibit tumor angiogenesis and growth in breast cancer by inhibiting the VEGFA-HIF pathway, and thus KLF2 may be an important anti-angiogenesis therapeutic target for breast cancer." (PMID 37123417, 2023). "Targeted inhibition of VEGFA prevents breast cancer invasion and angiogenesis." (PMID 37511521, 2023). "In addition, a previous study investigating the effect of conventional chemotherapy on tumor angiogenesis in breast cancer found that increased VEGFA expression correlated with tumor recurrence." (PMID 37686118, 2023). "We found that VEGFA mRNA level was significantly decreased after downregulation of LAMP2A in breast cancer cells, while LAMP2A overexpression could promote VEGFA mRNA expression level in breast cancer cells." (PMID 36913368, 2023).
breast cancer (continued). "Indeed, antiangiogenic therapy with bevacizumab, antibodies against vascular endothelial growth factor A (VEGF-A), or tyrosine kinase inhibitors such as sunitinib and pazopanib have been shown to effectively control metastatic breast cancer." (PMID 37736849, 2023). "Moreover, a study reported that EMT endows tumorigenicity to mice breast cancer cells through the upregulated expression of vascular endothelial growth factor A (VEGFA) and through enhancing tumor angiogenesis effect." (PMID 37781036, 2023). "Besides, reduced SERPINE1 can obviously impede the resistance of breast cancer cells to paclitaxel via inducing the inactivation of VEGFA." (PMID 36033831, 2022). "However, ERO1 loss of function is not fully compensated by PRDX4 and other oxidases: indeed, in previous work, we demonstrated a selective impairment of VEGFA-mediated angiogenesis in ERO1-devoid breast cancer under hypoxic conditions." (PMID 36063727, 2022). "Additionally, angiogenic factors including VEGFa and MMP9, REST target genes associated with migration and invasion of breast cancer cells, were upregulated in ER- or TNBC tumors." (PMID 35177031, 2022). "A study suggests that ACE2, a potential resister of breast cancer, may inhibit breast cancer angiogenesis through the VEGFa/VEGFR2/ERK pathway." (PMID 38091511, 2022). "Obesity-associated NLRC4 inflammasome activation could also mediate the adipocyte-mediated vascular endothelial growth factor A (VEGFA) expression and angiogenesis, which speed up the course of invasion in breast cancer." (PMID 36119049, 2022). "For example, IL-1β regulates the expression of adipocyte-mediated vascular endothelial growth factor A and angiogenesis, which may lead to the progression of breast cancer." (PMID 36147694, 2022). "Furthermore, we were able to demonstrate that cytoplasmatic VEGFA/165b expression is higher in invasive breast cancer tumor cells than in normal tissues or stroma." (PMID 35303290, 2022). "Taken all these results into consideration, VEGFA and EZH2 might be the most potential targets involved in the established m5C regulators-associated miRNA–mRNA network in breast cancer." (PMID 35812757, 2022). "However, it is still not clear about the effects of endocrine therapy and chemotherapy on the expression levels of FGF10 and VEGFA in breast cancer patients, which is also one of the important directions of our next research." (PMID 35668376, 2022). "Moreover, GPx2 KD resulted in abnormal intratumoral vessels that were long and tortuous, which were consistent with HIF1α and VEGFA up-regulation in GPx2 KD in mammary tumors." (PMID 35193955, 2022). "Moreover, expression correlation analysis suggested that DNMT3B was markedly positively associated with VEGFA and EZH2 in breast cancer." (PMID 35812757, 2022). "For instance, the transcription factor POU class 1 homeobox 1 (POU1F1, also known as Pit-1), a protein expressed by breast cancer cells, has been reported to increase macrophage recruitment and to promote their polarization towards VEGFA-expressing tumor-promoting macrophages." (PMID 35309358, 2022). "Overexpressed vascular endothelial growth factor A (VEGFA) and phosphorylated signal transducer and activator of transcription 3 (P-STAT3) cause unrestricted tumor growth and angiogenesis of breast cancer (BRCA), especially triple-negative breast cancer (TNBC)." (PMID 34059068, 2021). "The importance of VEGFA in breast cancer has been described in several studies." (PMID 34429108, 2021). "The Oncomine database also showed that the VEGFA expression level was increased in breast cancer." (PMID 34059068, 2021).
breast cancer (continued). "We hypothesize that S1PR1 could serve as a potent antitumor and antiangiogenic target in breast cancer by downregulating the P-STAT3/VEGFA pathway." (PMID 34059068, 2021). "PPARδ activation can stimulate the expression of VEGFA in breast cancer and prostate cancer." (PMID 34712608, 2021). "In this regard, we speculate that COPS5 may regulate VEGFA to promote breast cancer progression, although the mechanism between VEGFA and COPS5 needs to be further explored." (PMID 34993131, 2021). "Similarly, miR-9-mediated E-cadherin increases VEGFA expression in breast cancer via activating beta-catenin signaling in animal models and cell lines." (PMID 34778378, 2021). "To further elucidate whether miR-145-3p contributed to metastasis and angiogenesis of breast cancer, we evaluated the expression levels of VEGFA and CD33 by IHC." (PMID 34350110, 2021). "We further verified the effects of hypoxia enhancing miRNA-induced oxidative stress, cell migration, induction of EMT, expression of hypoxia-linked genes such as VHL, HIF-1α, and NFκB1, and expression of inflammation-associated genes such as VEGFA, COX-2, and EP4 in breast cancer cell lines." (PMID 32707933, 2020). "Thus, disruption of this microenvironmental juxtacrine/angiocrine loop at any level—such as Notch1 and VEGFA—severely diminishes the aggressiveness of breast cancer in vitro and in vivo." (PMID 33046710, 2020). "Moreover, ID4 enhances the angiogenic potential of breast cancer cells through the post-transcriptional regulation of IL8, CXCL1, and VEGFA mRNAs and through the reprogramming of tumor-associated macrophages." (PMID 32054109, 2020). "Leptin has been shown to up-regulate VEGFA expression in mouse mammary tumor cell lines." (PMID 32318345, 2020). "Selecting two types of BC cells could help us understanding whether miR-212-3p/Sp1/VEGFA signal axis could regulate different breast cancer subtypes." (PMID 33187481, 2020). "Therefore, Zeb1 depletion in breast cancer cells impairs VEGFA paracrine signaling in adjacent endothelial cells to subvert a Jag1-mediated perivascular niche." (PMID 33046710, 2020). "Moreover, miR-205 controls invasion in breast cancer by inhibiting Vascular Endothelial Growth Factor A (VEGFA), a known angiogenesis marker." (PMID 32854238, 2020). "Notably, our data further support the prognostic value of VEGFA rs833061 for breast cancer patients." (PMID 33238394, 2020). "It showed that Ursolic acid could bind to AKT1/VEGFA, then inhibited breast cancer growth through ErbB or Estrogen pathway." (PMID 32978480, 2020). "The microRNA and its target were important regulatory mechanism for LINC00511, such as miR-185-3p/E2F1 in breast cancer, miR29b-3p/VEGFA in pancreatic cancer, miR-15a-3p/Wnt signaling pathway in bladder cancer, miR-765/APE1 in osteosarcoma and miR-765/LAMC2 in tongue cancer." (PMID 31434692, 2019). "In addition, the Kaplan–Meier survival analysis showed that increased MIF and VEGFA expression levels in breast cancer patients correlated with a reduced survival rate." (PMID 31293831, 2019). "Many pro-angiogenic factors mediate tumour angiogenesis, and among these, VEGFa might play a major role in the process through which ACE2 inhibits breast cancer angiogenesis, as demonstrated through our database analysis." (PMID 31023337, 2019). "Interestingly, the low survival probability of patients that co-express HMGA1, FOXM1 and VEGFA at high levels has also been observed both in breast cancer datasets and in a subset of TNBC patients." (PMID 31311575, 2019). "Thus, the findings suggested that VEGFa played a role in the anti-angiogenetic effect of ACE2 in breast cancer." (PMID 31023337, 2019). "Similarly, the target relation between miR-205 and VEGFA has also been unraveled in patients with breast cancer." (PMID 31719795, 2019). "Prospectively, VEGFA may act as an evaluation factor to identify breast cancer patients who might benefit from antiangiogenic therapy." (PMID 31293831, 2019).
breast cancer (continued). "Furthermore, osteopontin regulates the ICAM-1 and VEGFA expression mainly in triple-negative/basal-like breast cancer, supporting its role in tumor progression in TNBC." (PMID 31731625, 2019). "ACE2 downregulated the expression of VEGFa in breast cancer cells." (PMID 31023337, 2019). "Moreover, in a TCGA dataset of breast cancer patients, we found an enrichment of VEGFA mRNA in HMGA1 or FOXM1 overexpressing patients." (PMID 31311575, 2019). "Our findings suggest that ACE2, as a potential resister to breast cancer, might inhibit breast cancer angiogenesis through the VEGFa/VEGFR2/ERK pathway." (PMID 31023337, 2019). "Our previous study showed that hypoxia, a common feature of solid tumors, could induce VEGFA expression and angiogenesis in breast cancer cells and tumor-bearing mice by activating the ATM–SerRS pathway." (PMID 31766690, 2019). "Even though FOXO3A has not been found to possess direct methylating or demethylating properties, FOXO3A binding has been linked to the recruitment of HDAC1 to the VEGFA promoter in MDA-MB-231 cells, a metastatic breast cancer cell line, similar to our findings in SCC-25 cells." (PMID 30978209, 2019). "On the other hand, in breast cancer VEGFA-189 may possess anti-tumor functions since it reduces invasion and metastatic potential of tumor cells and promotes apoptosis in stress conditions." (PMID 29888133, 2018). "Interestingly, bevacizumab, an antibody that inhibits VEGFA function and thus angiogenesis, altered the expression of Vldlr in basal-like breast cancer and Arhgap6 in endometrial cancer." (PMID 28423599, 2017). "Thus, expression levels of p38MAPK targets FN1 and VEGFA are elevated in breast cancers and a high level of these factors is an unfavorable marker of disease recurrence and poor-outcome." (PMID 28977919, 2017). "Here, we showed that compression induces miR-9 downregulation via DNMT3A-dependent promoter methylation, which leads to the upregulation of miR-9 target genes (LAMC2, ITGA6, and EIF4E) thus potentiating signal transduction for VEGFA expression in CAFs and breast cancer cells." (PMID 28252641, 2017). "We have found that the expression of VEGFA, which is an important signal molecule released by cells that promotes vasculogenesis and angiogenesis, was apparently lowered by high‐dose CLOs in rat mammary carcinomas in vivo." (PMID 28524540, 2017). "First, as presented in this study, ZEB1 may induce VEGFA production by breast cancer cells through activation of the PI3K and p38 pathways." (PMID 26882471, 2016). "We have shown increased expression of VEGFA, which play a crucial role in the stimulation of angiogenesis via signaling through VEGF receptor 2, and GRB-7, which expression was shown to be strongly associated with decreased survival of breast cancer patients." (PMID 26759169, 2016). "Positive correlation between ZEB1 and VEGFA expression in breast cancer." (PMID 26882471, 2016). "Importantly, ZEB1 expression is positively correlated with VEGFA expression and blood vessel density in human breast cancer specimens." (PMID 26882471, 2016). "Finally, we also measured VEGFa mRNA expressed in the mammary tumors with knockout of Ncoa3, another member of the SRC family." (PMID 26287601, 2015). "Several lines of evidence implicate the importance of VEGFA in breast cancer." (PMID 23203097, 2012). "Vascular endothelial growth factor-A is considered to be the most crucial regulator of angiogenesis and vasculogenesis and its expression has been demonstrated in cancer cells of various human tumours including breast cancer." (PMID 15841074, 2005). "Bevacizumab (Bev), a humanized monoclonal antibody targeting vascular endothelial growth factor A (VEGF-A), is primarily used for the treatment of various solid tumors, such as colorectal cancer, non-squamous non-small cell lung cancer, renal cell carcinoma, and breast cancer." (PMID 38996149, 2024).
breast cancer (continued). "Moreover, we found that CMA could promote VEGFA expression in breast cancer cells and in xenograft model through upregulating lactate production." (PMID 36913368, 2023). "Therefore, according to the results of all GO and KEGG analyses, FGF10 and VEGFA might play an important role in the development of second primary lung cancer in breast cancer patients." (PMID 35668376, 2022). "Furthermore, the mutations of TRIM73, DLX6 and CNGB1 and high expression of FGF10 and VEGFA might play an important role in the development of lung adenocarcinoma in breast cancer patients." (PMID 35668376, 2022). "Additionally, the VEGFA presence was reported in human breast cancer specimens." (PMID 36230822, 2022). "VEGFa might play a key role in the process of inhibiting angiogenesis by ACE2 in breast cancer." (PMID 34413267, 2021). "Hypoxia could induce miR‐153 expression via triggering ER stress, and miR‐153 directly inhibited expression of the hypoxia‐inducible factor 1‐alpha and suppresses breast cancer angiogenesis by decreasing the secretion of vascular endothelial growth factor A (VEGFA)." (PMID 34320274, 2021). "Therefore, the mechanism of ACE2 to inhibit angiogenesis of breast cancer might be related to VEGFa/VEGFR2/ERK pathway." (PMID 34413267, 2021). "Moreover, as we previously observed that the ID4 protein controls VEGFA expression in breast cancer cells, and VEGFA in turn participates in the reprogramming of macrophages in a pro-angiogenic sense, we decided to investigate the impact of VEGFA on ID4 and ARNT expression in macrophages." (PMID 32054109, 2020). "Therefore, the VEGFa/VEGFR2/ERK pathway might be the mechanism by which ACE2 inhibits breast cancer angiogenesis and metastasis." (PMID 31023337, 2019). "Therefore, CAPE-pNO2 against the growth and metastasis of breast cancer might be via restraining MMP-2, MMP-9, and VEGFA expression, and these proteins were associated with the EGFR/STAT3/Akt signaling pathway." (PMID 31214503, 2019). "Therefore, ACE2 inhibits breast cancer angiogenesis by the VEGFa/VEGFR2/ERK pathway." (PMID 31023337, 2019). "However, ACE2, as an upstream mediator of VEGFa, could inhibit breast cancer angiogenesis and might thus be a promising therapeutic target to postpone the progression of breast cancer." (PMID 31023337, 2019). "In conclusion, our current study show miR-16-5p is significantly downregulated in breast carcinoma, and its overexpression contributes to growth inhibition in vitro and in vivo, cell apoptosis and the decrease of invasion ability, which is at least in part achieved by directly targeting VEGFA." (PMID 29069797, 2017). "Thus the chemo-sensitizing effect of miR-205 in breast cancer depends on VEGFA/FGF2 downregulation." (PMID 27362808, 2016). "Moreover, immunohistochemical staining of samples from 4 representative subjects confirmed the positive relationship between ZEB1, VEGFA, and CD31 expression, which is consistent with our finding that ZEB1 upregulates VEGFA expression and promotes tumor angiogenesis in breast cancer." (PMID 26882471, 2016). "Knockout or knockdown of NCOA1 in breast cancer cell lines also markedly compromised their capability to induce angiogenesis in Matrigel plugs embedded subcutaneously in mice, while this compromised capability could be rescued by VEGFa treatment." (PMID 26287601, 2015). "In addition to having a pivotal role in basal breast cancer growth and metastasis, the secreted factors implicated in our previous study (IL6, CSF2, CCL5, VEGFA, and VEGFC) may also serve critical roles in other subtypes of breast cancers." (PMID 26173622, 2015). "However, VEGFA expression is down-regulated by E2 in human breast cancer cells." (PMID 22609851, 2012).